IGF1 (insulin like growth factor 1)
Diseases named in the same sentence as IGF1 in open-access papers (continued):
Sharing a sentence is not in itself a finding about the gene and the disease.
Cognitive impairment (continued). "It was shown that such cognitive impairments were reversible by extended systemic administration of IGF-1, pointing that the neurotrophic actions of IGF-1 influence glutamatergic synapses within the hippocampal circuits, thus affecting learning and memory." (PMID 29093741, 2017). "The dysregulation of synaptic maturation and disruption of IGF1 downstream signaling pathways are both involved in some of these cognitive disorders, including diabetic encephalopathy." (PMID 25268761, 2014). "The purpose of this review is to assess the complex roles of IGF-1 in the genesis of cognitive impairment with age." (PMID 23847531, 2013). "The pivotal roles of insulin and IGF-1 resistance as mediators of cognitive impairment and neurodegeneration have been well documented in humans and experimental animals." (PMID 25035815, 2013). "The role of IGF1 in cognitive deficits and neuroinflammation during HE remains largely unexplored." (PMID 42074188, 2026). "In the present study, we hypothesized that peripheral nerve injury induces comorbid neuropathic pain and cognitive impairment by disrupting the WNT3/IGF‐1 axis in the dorsal DG." (PMID 41414737, 2025). "Targeting metabolic- and plasticity- related systems by augmenting insulin and IGF-1 signaling may be considered a therapeutic strategy for reducing AUD-related cognitive deficits." (PMID 41400881, 2025). "These brain regions are associated with emotion, cognition and memory, supporting the idea that reducing IGF-1, which leads to impaired function in these areas, may lead to memory disorders and cognitive impairment that are common in aging." (PMID 39963470, 2025). "The functional significance of this pathway is underscored by our rescue experiments: local administration of IGF‐1 into the dorsal DG reversed both nociceptive hypersensitivity and cognitive impairment in SNI mice, with these effects abrogated by IGF‐1R antagonism or PI3K/AKT inhibition." (PMID 41414737, 2025). "Thus, interventions that raise BDNF and IGF-1 levels are expected to become potential targets for the treatment of cognitive impairment and Alzheimer’s disease in the near future." (PMID 38961824, 2024). "IGF-1 levels tend to decrease with age and negatively correlate with cognitive impairment." (PMID 38542318, 2024). "Inhibition of miR-129 by miR-129 antagomir could attenuate NLRP3/caspase-1 mediated pyroptosis and improve cognitive impairment by activating IGF-1/GSK3β signaling pathway via directly targeting IGF-1." (PMID 37332874, 2023). "On the contrary, other studies have reported that these cognitive disorders may improve after controlling GH and IGF-1 hypersecretion." (PMID 36983284, 2023). "Moreover, among patients with multiple sclerosis, patients with cognitive impairment had significantly lower level of IGF-1 than those with normal cognition." (PMID 37638322, 2023). "Hence, the abnormal development of the DG in premature infants contributes to cognitive deficits and is mediated by IGF1." (PMID 37594177, 2023). "The mechanism of cognitive impairment in patients may result from a combination of factors in which GH and IGF-1 play an essential role." (PMID 36983284, 2023). "Some studies have reported decreased IGF-1 levels in patients with cSVD and an association with cognitive impairment; however, the exact mechanism is not known." (PMID 37358957, 2023). "In this study, we applied the Morris water maze to assess the cognition in TBI mice and found that astrocytic IGF-1 could reduce the cognitive impairment as well and the path tracing demonstrated the learning procedure in these rodents." (PMID 36062186, 2022). "Low serum IGF-1 levels correlated with cognitive impairment and fatigue in MS patients." (PMID 36141293, 2022). "In conclusion, results presented in this work indicate that brain focalized IGF-1 over-expression could be an effective therapeutic approach targeting neuroinflammation and also improving the cognitive deficits observed after TBI." (PMID 34234671, 2021).
Cognitive impairment (continued). "Interestingly, AOPP, and MDA levels in the studied brain areas were significantly reduced after IGF-1 gene therapy that in turn prevented cognitive deficits, restoring TBI-animals working memory performance to similar values regarding control." (PMID 34234671, 2021). "However, more studies are needed with interventions in older adults to deepen the potential of cardiorespiratory fitness and strength training in the variables of cognitive impairment and physiological indicators such as IGF1." (PMID 33920935, 2021). "It has been demonstrated that miR-29 family is the microglial modulators of the insulin-like growth factor-1 (IGF-1) and fractalkine ligand (CX3CL1), supporting the hypothesis that impairment of IR and IGF-1 mediates cognitive impairment in AD." (PMID 32674523, 2020). "In animal studies, some researchers have suggested that GH/IGF-1 administration can decrease Ab1–40 protein levels, which may contribute to age-related cognitive deficits, and promote improvements in learning and memory in aged animals with AD." (PMID 31967977, 2020). "Circulating IGF-1 may decline when the condition of PD deteriorates to the stage with the complication of cognitive impairment." (PMID 29865234, 2018). "For serum IGF-1 levels, the Q1 and Q2 groups had significantly greater odds to be with cognitive impairment (OR 8.43, 95% CI (2.4 ± 4.9), P < 0.001 and OR 3.01, 95% CI (0.3 ± 1.2), P = 0.03), while the odds for the Q3 group was OR 2.9, 95% CI (0.59 ± 1.4), p = 0.7." (PMID 30294204, 2018). "The promising procognitive effects seen with GH and IGF-1 treatment, as well as the neuroprotective properties, suggest that GH and IGF-1 may be effective pharmacological interventions for opioid-induced cognitive impairment." (PMID 30453639, 2018). "However, low serum levels of IGF-1 have significantly greater odds for fatigue (P = 0.002) and cognitive impairment (P < 0.001)." (PMID 30294204, 2018). "The results, specifically that low levels of serum IGF-1 was associated with cognitive impairment and fatigue in MS, suggest that IGF-I may be involved in the pathogenesis of cognitive deficits and fatigue in MS disease." (PMID 30294204, 2018). "In conclusion, insulin and IGF-1 may alleviate cognitive impairment in PD via the inactivation of GSK3β mediated by PI3K/Akt." (PMID 29515352, 2018). "Evidence supports the hypothesis that insulin-like growth factor-1 (IGF-1) is involved in cognitive deficits." (PMID 29065116, 2017). "However, as there is a dearth of consistent serum biomarkers in PD, our intent was to focus on the role of serum IGF-1 as possible marker of cognitive impairment in a large cohort of early stage PD." (PMID 29065116, 2017). "Therefore, taken together the findings from the current and previous study support the link between IGF-1 and cognitive impairment in PD patients even in the earliest stages of disease." (PMID 29065116, 2017). "Given that IGF-1 is a key partner of the actions of insulin, insulin levels may also influence the disease cognitive impairment." (PMID 27627435, 2016). "Rodents have a similar decrease in circulating IGF-1 levels with age and intra-cerebroventricular (icv) IGF-1 replacement to older F344xBN rats, which increases concentrations of IGF-1 in the hippocampus to levels found in young animals, reverses these cognitive deficits." (PMID 23847531, 2013). "Given that IGF-1 deficiency occurs in up to 66% of TBI survivors, it is plausible that chronic IGF-1 dysregulation may contribute to long-term cerebrovascular dysfunction and cognitive impairment in this population." (PMID 40360822, 2025). "Supportive of this hypothesis are several studies, which found that exergaming increased BDNF levels in chronic stroke, older adults and Parkinson’s disease patients, as well as IGF-1 and other neuroplasticity-indicative biomarkers in people with mild cognitive impairment." (PMID 40182756, 2025).
Cognitive impairment (continued). "This experiment was carried out to determine if exogenous supplementation of IGF-1 could alleviate cognitive dysfunction in OSAS rats by subcutaneous injection of IGF-1 into the abdomen of OSAS rats based on the therapeutic potential of IGF-1 in cognitive disorders." (PMID 38858326, 2024). "It is currently unknown, nevertheless, if IGF-1 can treat OSAS-related cognitive impairment." (PMID 38858326, 2024). "However, T3D-959 treatment, an orally active brain-penetrating PPARδ/γ dual nuclear receptor agonist and a potent insulin sensitizer, ameliorated cognitive deficits and AD pathological hallmarks via promoted expression of insulin/IGF-1/Akt signaling proteins in the temporal lobes." (PMID 32719587, 2020). "Thus, studies conducted in the last 20 years support the hypothesis that deficits in brain insulin and insulin-like growth factor (IGF-1) signaling mediate cognitive impairment and neurodegeneration in AD." (PMID 31551756, 2019). "As both GH and IGF-1 display promising effects with respect to cognition and neuroprotection, it is possible that these hormones can be used as viable treatments for cognitive impairments in the CNS.Accumulating evidence suggest that opioids such as methadone may induce cognitive disorders." (PMID 30453639, 2018). "Although the major white matter tracts with a central role in cognitive impairment and dementia, and with fundamental associations with motor severity showed altered connectivity in correlation with serum IGF-1 levels, there was no such association with white matter FA, MD, RD, or AD values." (PMID 30450079, 2018). "Therefore, the current case control study was designed to investigate whether in MS patients circulating serum levels of IGF-1 has been found to be related to cognitive impairment and fatigue." (PMID 30294204, 2018). "Despite these advances, the mechanisms by which peripheral nerve injury disrupts IGF‐1 and WNT3 signaling in the DG—and how such disruptions contribute to comorbid pain and cognitive impairment—remain poorly understood." (PMID 41414737, 2025). "For example, a meta-analysis involving 514 individuals with mild cognitive impairment (MCI) demonstrated that physical activity led to increased BDNF and IGF-1 concentrations." (PMID 38961824, 2024). "An independent study observed an increase in the cGP/IGF-1 molar ratio and a decrease in the IGFBP-3 concentration in older people with mild cognitive impairment, suggesting an ineffective response to overcome age-related cognitive decline." (PMID 36770687, 2023). "The IGF-1 level in the body decreased with aging, and in the elderly with mild cognitive impairment (MCI), aerobic exercise intervention lasting for 18 months can significantly increase the serum IGF-1 level and improve cognitive ability." (PMID 37638322, 2023). "In summary, moderate cognitive impairment in fs-IQ, VCI, WMI, PRI, and PSI were shown in GHD children, suggesting a possible protective effect of the GH/IGF-1 axis in cognitive function." (PMID 36685242, 2022). "The effect of cognitive impairment on plasma levels of BDNF, 3-NT, IGF-1, IGF-2 and IGFBP-3 was evaluated using Student’s t test." (PMID 34341419, 2021). "The aim of this study was to determine the effects of a muscular strength programme on the levels of insulin-like growth factor-1 (IGF-1) and cognitive status in elder women with mild cognitive impairment who lived in areas of high air pollution." (PMID 32859109, 2020). "Therefore, some evidence indicates that interventions to mitigate IGF-1 deficiency (i.e., exercise programmes) would improve cognitive state, however, it seems that further investigation is needed to know if this association exists between IGF-1 and cognitive impairment." (PMID 32859109, 2020). "Treatments aimed at restoring IGF-1 brain levels in MCAO rodent models reduced the infarct volume and the rate of apoptosis, improving cognitive deficits through the IGF-1/AKT pathway." (PMID 31096580, 2019).
Cognitive impairment (continued). "IGF-1 resistance, characterized by the increase of circulating IGF-1 with impaired IGF-1 function, plays a role in disease progression, cognitive impairment, and pathology of idiopathic PD." (PMID 29865234, 2018). "Thus, associations of PD and elevated IGF-1 might best be shown in PD patients without cognitive impairment or β-amyloid pathology." (PMID 26967642, 2016). "These cognitive impairments were reversible by prolonged systemic administration of IGF-1 and suggested that the neurotrophic actions of IGF-1 affect glutamatergic synapses within the hippocampal circuitries, thereby affecting learning and memory." (PMID 26417600, 2015). "Replacement of IGF-1 or factors that increase IGF-1 to old animals and humans reverses many of these cognitive deficits." (PMID 23847531, 2013). "Critically, pretreatment with the IGF‐1R antagonist JB‐1 (0.8 μM in 0.5 μL) or the AKT inhibitor LY294002 (0.8 μM in 0.5 μL) abolished the therapeutic effects of IGF‐1 in SNI mice, implicating IGF‐1R/AKT signaling in the observed rescue of nociceptive and cognitive deficits." (PMID 41414737, 2025). "We further tested whether targeted restoration of IGF‐1 or WNT3 function in the dorsal DG could reverse pain sensitization and cognitive deficits and explored the mechanistic interplay between these pathways." (PMID 41414737, 2025). "Instead, the wild-type IGF-1 allele and non-wild type TNF-alpha allele were closely associated with cognitive impairment outcomes." (PMID 39061961, 2024). "This increase in the cGP/IGF-1 molar ratio is absent in the PD group with mild cognitive impairment (PD-MCI)." (PMID 36770687, 2023). "The authors also pointed out that a significant increase in IGF-1 levels can occur among children who recovered their cognitive function, whereas in children without cognitive deficits, a decreased rather than increased IGF-1 concentration can be expected." (PMID 36120463, 2022). "And old people with cognitive impairments have lower serum IGF-1 levels compared with those without." (PMID 36685242, 2022). "Women with mild cognitive impairment improved on multiple cognitive tests in response to exercise but without changes in IGF-1 plasma levels." (PMID 32785144, 2020). "Considering that patients with low CSF IGF-1 do not respond well to therapy, an association between IGF-1 levels and subsequent degree of developmental and cognitive impairment has been proposed." (PMID 31156384, 2019). "The study demonstrated a favorable effect of GHRH administration in adult patients with mild cognitive impairment, independent of the IGF-1 level that did not change significantly." (PMID 29149058, 2017). "Palomino et al24 found a positive correlation between the scales of negative symptoms, including cognitive deficits, and peripheral IGF-1 concentration." (PMID 26825882, 2016). "Because IGF1 and IGF2 activate the same receptor, IGF2 may have some utility in reversing some of the cognitive deficits in PTHS patients." (PMID 24058414, 2013). "Contrary to our finding, the down-regulation of IGF1R and its ligand IGF1 was observed in the hippocampus of rats with vascular dementia and the treatment of mice with an IGF1R agonist alleviated the white matter damage and cognitive deficits after cerebral hypoperfusion." (PMID 36771351, 2023). "While the role of IGF-1 in various aspects of neural development, plasticity and general pro-cognitive effects have been long established, the focus has now shifted to recognizing the impact of IGF-1 decrease on cognitive impairment, as well as other neurological conditions." (PMID 35563873, 2022). "By showing that IGF-1 is an important mediator of the beneficial effect of the neural-endocrine network in TBI models, our findings place IGF-1/IGF-1R as a potential target capable of noncoding RNAs and opposing mitophagy failure and cognitive impairment in TBI." (PMID 36062186, 2022).
Cognitive impairment (continued). "An excess of GH and IGF-1 lead to anatomical changes in craniofacial bones, soft tissues, and respiratory mucosa, so these patients often develop OSAS (as many as 80-90% in some series) day time narcolepsy, and cognitive impairment severe enough the quality of life." (PMID 28490347, 2017). "Thus, it can be assumed that the age-dependent decline in the expression of both IGF-1 and IGF-1 receptor could be a possible contributing factor to the development of cognitive deficits seen in the elderly." (PMID 26417600, 2015). "Additionally, IGF-1 gene therapy was found to improve cognitive function in a mouse model of ischemic stroke, suggesting that IGF-1 may play a role in cognitive impairment due to cSVD." (PMID 37358957, 2023).